IL4 (interleukin 4)
Diseases named in the same sentence as IL4 in open-access papers (continued):
Sharing a sentence is not in itself a finding about the gene and the disease.
asthma (continued). "The approved humanized monoclonal antibodies (mAbs) for the treatment of asthma are targeted against IgE (omalizumab), IL-5 (mepolizumab and reslizumab), IL-5 receptor α (IL-5Rα; benralizumab), and IL-4/IL-13 (dupilumab)." (PMID 34572466, 2021). "To evaluate the function of filaggrin in bronchial cells upon the on-set of asthma, we simulated the cytokine environment in asthma with Th2 cytokine IL-4." (PMID 34484176, 2021). "In asthma models of mice, quercetin reduced levels of IL-4 and Th2 cytokine, but increased IFN-γ and Th1 cytokine production which indicates the therapeutic effect of quercetin on asthma by improving Th1/Th2 balance." (PMID 34567150, 2021). "This review summarizes the IL-4 and IL-13 pathways while highlighting and discussing the current pathway inhibitors aimed at treating thunderstorm asthma and atopic dermatitis, as well as the potential efficacy of peptide therapeutics in this field." (PMID 34948449, 2021). "created a recombinant bifunctional IL-4/IL-13 antagonist that in a mouse of model of asthma reduced not only IL-4–dependent increase in serum IgE levels but also IL-13–dependent airway hyper-responsiveness and lung inflammation." (PMID 34305927, 2021). "A previous study has shown that bronchoalveolar lavage samples with elevated CD4+ cells that expressed both IL-4 and IL-17 predicted greater asthma severity." (PMID 35387066, 2021). "An increase in the levels of Th2 cytokines (IL-4, IL-5, and IL-13, among others) and Th17 cytokines (IL-17 and IL-6, among others) was observed in both patients with asthma and animal models of asthma." (PMID 34526979, 2021). "Serum IL-4, IL-9, and IL-13 levels were significantly (p < 0.01) enhanced in the asthma group compared with the control group." (PMID 33577738, 2021). "The activation of Th2 lymphocytes is a significant factor in the development of asthma, which can stimulate the synthesis of IgE and the infiltration of inflammatory cells by releasing representative cytokines such as IL-13, IL-4, and IL-5." (PMID 33628113, 2021). "This includes more Th1 cytokines (IFN-γ and IL-2) combined with fewerTh2 cytokines (IL-4 and IL-5), correlated with significantly higher NK cell cytotoxicity as compared to the asthma group." (PMID 33919400, 2021). "Th2 and ILC2-derived IL-4, IL-5, and IL-13 generate the typical pathophysiological effects of asthma, including activation and recruitment of eosinophils in the airways, IgE production by activated plasma cells, AHR and airway remodelling." (PMID 34020658, 2021). "This study revealed the active ingredients and potential molecular mechanism by which MGMD treatment is effective against airway inflammation and remodeling in asthma through regulating IL-4 and IL-13 signaling and SPMs biosynthesis." (PMID 33968984, 2021). "As a proof of concept, these treatments have illustrated that the inhibition of the IL-4 and IL-13 pathways can effectively treat thunderstorm asthma, although costs and administration must improve before they can be considered as treatments." (PMID 34948449, 2021). "IL-4 and IL-13, which are produced by inflammatory cells including type 2 helper T cells during allergic inflammation including asthma, are known to induce the expression of iNOS in airway epithelial cells." (PMID 34782693, 2021). "Nowadays, available biological asthma therapy is reserved for T2-high asthma; it targets allergy molecules IgE and eosinophilic interleukins (IL-5, IL-4, IL-13, TSLP)." (PMID 34070316, 2021). "Chronic airway inflammation in asthma is typically characterized by eosinophil infiltration, overproduction of IgE, and Th2 cytokines, including IL-4, IL-5, and IL-13." (PMID 35008504, 2021). "Novel biologics such as IL5 and IL-4/IL-13 pathway-targeting therapies have made essential the phenotyping of severe asthma, according to GINA guidelines." (PMID 33815653, 2021).
asthma (continued). "In asthma, type III Interferons have been reported to decrease IL-4 and IL-5 production, as well as IL-13 production by T cells providing evidence for a protective role in asthma exacerbations." (PMID 34899691, 2021). "Th2-dominant responses, with increased Th2 (IL-4, IL-5, and IL-13) cytokines and IgE production, are characteristic immune responses in patients with allergic diseases such as food allergy, asthma, and AD." (PMID 34356353, 2021). "In mice that lack IL-4, IL-5, IL-13 reduction of asthma symptoms was observed in the Ova-Alum experimental model." (PMID 33649900, 2021). "Based on our results, we summarize that TGF-β signaling, cell cycle related, and IL-4 and IL-13 signaling pathways are important in determining responses to ICSs in patients with asthma." (PMID 33816533, 2021). "Pathophysiological and inflammatory processes in T2-high asthma are represented by a high level of type 2 cytokines: IL-5, IL-4, IL-13, IL-25, IL-33, and thymic stromal lymphopoietin (TSLP)." (PMID 34070316, 2021). "We also investigated the effect of VitD supplementation on the expression of proinflammatory cytokines involved in asthma pathogenesis, including Th2 cytokines (IL-4 and IL-5) and Th17 cytokines (IL-17A and IL-17F)." (PMID 34395637, 2021). "Here the authors show, in humanized mouse models, that dual vaccination against IL-4 and IL-13 induces their durable suppression ameliorate experimental asthma, and to hint clinical translation." (PMID 33976140, 2021). "The Th2 pathway in asthma can be recognized by increased secretion of IL-4, IL-5, and/or IL-13 resulting in eosinophilic inflammation." (PMID 35387016, 2021). "About half of all asthma patients have such an eosinophilic airway inflammation and corticosteroids, anti-IgE, anti-IL-5/IL-5R, and anti-IL-4/IL-13 treatment are effective at alleviating the symptoms." (PMID 34061861, 2021). "Dupilumab, a monoclonal antibody against human IL-4 receptor α, inhibits both IL-4 and IL-13 signaling and has been confirmed to be effective in phase 3 clinical trials of asthma and atopic dermatitis." (PMID 34194433, 2021). "Another study found an association between a Mediterranean diet pattern and lower levels of IL-4 and IL-17, but higher levels of IL-33, in both males and females with asthma." (PMID 33503979, 2021). "In this case, H4 acetylation of IFN-γ and deacetylation of IL-4 promoter genes result in the downregulation of Th2 cytokines, showing transmaternal asthma protection." (PMID 34566492, 2021). "Due to the integral role that the IL-4 pathway plays in allergen-induced asthma, it is a prime candidate for inhibitory drugs to treat allergic asthma." (PMID 34948449, 2021). "Research evidence points to an increased IL-4, Th17 and the levels of serum mTOR as playing a key role in asthma development." (PMID 34069141, 2021). "Another mediator related to eosinophils and the inflammatory process of asthma is Th2 cytokines, such as IL-4 and IL-51,30,38,58." (PMID 34521963, 2021). "Approved therapeutic monoclonal antibodies targeting IgE or IL-4/IL-13 reduce asthma symptoms but require costly lifelong administrations." (PMID 33976140, 2021). "Th2 type of response is one of the main concepts in asthma pathogenesis; here, we consider all γδ T cells producing any of Th2 cytokines (IL-4, IL-5 or IL-13) as Th2-like γδ T." (PMID 33661375, 2021). "Asthma is characterized by chronic inflammatory infiltration caused by inflammatory cells and immune cells, and inhibition of TNF-α, IL-1β, IL-17, IL-4, and IL-6 contributes to improving asthma." (PMID 35069542, 2021). "Unfortunately, no studies thus far have looked at the efficacy of combining anti-IL-4/IL-13 and anti-IL-5 biologics for asthma treatment." (PMID 35126131, 2021). "The cytokines (IL-4, 5, 6, 10, and 13) produced by Th2 cells have been shown to play pivotal roles in the development of eosinophilic inflammation in asthma, while interleukin-2 and interferon-γ were produced by Th1 cells." (PMID 33859559, 2021).
asthma (continued). "The elite group of susceptible genes of asthma and atopy replicated in more than ten different studies include IL13, IL4, IL4RA, FCER1B and ADRB2, five important inflammatory genes associated with IgE levels." (PMID 34243801, 2021). "Whereas IL4 acts predominantly in the early phase of asthma development, IL13 is thought to be active in the late phase of allergic reactions." (PMID 34305924, 2021). "Eighty percentage of children and 60% of adults with asthma have type 2/Th2 asthma, which is driven by allergen-induced production of IgE and Th2 cytokines, including IL-5, IL-13, and IL-4." (PMID 33643321, 2021). "IL-4, IL-5 and IL-13 are the central Th2 cytokines responsible for eosinophilic inflammation in asthma." (PMID 34084159, 2021). "Total and most differential WBC counts and BALF levels of PLA2, TP, IgE, IL-4, and oxidants in asthma group were higher but antioxidants and IFN-γ levels as well as IFN-γ/IL-4 ratio were lower than control group (p < 0.001 for all cases)." (PMID 34804178, 2021). "Cytokine or cytokine receptor targeting by therapeutic antibodies, such as anti-IL-4 and anti-IL-5, is now approved for severe asthma treatment." (PMID 34084159, 2021). "The effects of nicotine-containing e-cigarettes on murine model asthma increased Th2 cytokines (IL-4, IL-5, and IL-13), responsible for allergic inflammation." (PMID 33924379, 2021). "For example, patients switched from anti-IL-5 to anti-IL-4/IL-13 had worsening in asthma control and showed increased use of OCS, with substantial increases in peripheral eosinophils." (PMID 35126131, 2021). "The STAT1 and STAT4 pathways are considered vital for Th1 differentiation, while the IL-4/IL-13/STAT-6 pathway has been confirmed to be the major modulator of Th2 differentiation in asthma pathophysiology." (PMID 34093516, 2021). "We now understand that, depending on disease severity, 40%–70% of patients with asthma exhibit heightened Type-2 (T2) inflammation, which clinically improves with IL-4– and IL-5–targeted therapies." (PMID 34591794, 2021). "An area of evolving interest relates to the therapeutic blockade of IL-4 signaling pathway to treat atopic dermatitis and asthma." (PMID 34557875, 2021). "IL-4 and IL-13 are thought to play an important role in asthma pathogenesis by inducing eotaxin (an eosinophil chemoattractant), increasing mucin glycoproteins (and causing mucous hyperplasia), and augmenting IgE-related hypersensitivity reactions." (PMID 33653328, 2021). "IL-4 and IL-13 are principal regulatory cytokines mainly secreted by activated Th2 cells, crucially important during the immune response in allergy and asthma." (PMID 33968984, 2021). "This function is in addition to the known roles of PI3Kδ in allergic asthma such as; leucocyte migration into inflamed tissues, release of asthma relevant cytokines (IL4 and IL5) and chemokines (RANTES and eotaxin)." (PMID 34920698, 2021). "AR upregulation decreases the expression of Th2 and Th17 cells, reduces IL-4 production in lungs, and decreases neutrophilic inflammation in severe asthma." (PMID 35096261, 2021). "Th2 cytokines, including interleukin (IL)‐4 and IL‐13, are closely related to various allergic diseases including asthma." (PMID 33534941, 2021). "In contrast, in a study assessing the impact of manipulation of the PD-L1 and PD-L2 pathways on the development of asthma, it was reported that blockade of the PD-L2 pathway led to increased airway inflammation, IL-4, and AHR." (PMID 33968057, 2021). "An alternative source of IL‐4 and IL‐13 are mast cells, a cell population increased within the peripheral airways of severe asthma and whose activation is poorly supressed by steroid therapy." (PMID 33411348, 2021). "Our previous study has developed a four‐gene model involving IL13 rs20541, IL4 rs2243250, ADRB2 rs1042713, and FCER1B rs569108 associated with asthma and atopy in Chinese Han children." (PMID 33277970, 2021).
asthma (continued). "Five key inflammatory genes affecting IgE levels, including IL13, IL4, IL4RA, FCER1B and ADRB2, have been demonstrated associated with asthma or atopy by more than ten different studies." (PMID 34243801, 2021). "Blocking IL4/IL-13 yielded promising results in Th-2-induced diseases, such as asthma or atopic dermatitis." (PMID 34831223, 2021). "Lebrikizumab and tralokinumab, IL-4/IL-13 inhibitors, show clinical efficiency in asthma and AD indication for the shared inflammatory mechanisms in the atopic diseases pathogenesis." (PMID 34911576, 2021). "Asthma pathophysiology involves alternative activation of macrophages by Th2 cytokines, such as interleukin 4 (IL‐4) or IL‐13." (PMID 33945658, 2021). "The increase of IL-4 and suppression of IL-10 is a valuable tool to show the promotion of asthma in rats sensitized to OVA." (PMID 33794910, 2021). "Researchers developing a new approach of dual IL-13/IL-4 inhibition (dupilumab), reported a therapeutic achievement with a higher clinical relevance for asthma treatment." (PMID 34572281, 2021). "SOCS1 is a negative regulator of IL-4-dependent pathway, resulting in the regulation of IgE, IL-4 and IL-13 levels, as well as the eosinophilic mucosal inflammation in asthma." (PMID 34629023, 2021). "The most common type of asthma is allergic or eosinophilic asthma, which is characterised by a type 2 immune response (driven by cytokines IL-4, IL-5 and IL-13) and IgE-mediated hypersensitivity." (PMID 34630416, 2021). "The chronic airway inflammation of asthma is characterized by the release of type 2 T helper cell cytokines, such as IL-4 and IL-13." (PMID 33407872, 2021). "T2 asthma is characterized by airway inflammation driven by T2 cytokines including interleukins IL-4, IL-5, and IL-13." (PMID 33513844, 2021). "Our results revealed the active ingredients and potential molecular mechanism by which MGMD treatment is effective against airway inflammation and remodeling in asthma through regulating IL-4 and IL-13 signaling and SPMs biosynthesis." (PMID 33968984, 2021). "And PLE treatment also significantly decreased the level of IL-4 and the ratio of IL-4/IFN-γ, suggesting a regulatory effect on Th1/Th2 imbalance which causes the pathogenesis of asthma." (PMID 34045925, 2021). "The essential roles of IL-4 and IL-13 in the pathogenesis of allergic diseases, such as AD and asthma, were proven clinically by the efficacy of dupilumab, a monoclonal antibody for IL-4Rα." (PMID 34691223, 2021). "Not only CS can induce DAMP release, as ovalbumin-sensitized mice display increased HMGB1 expression, but also the addition of exogenous HMGB1 increases Th2 cells and asthma-related cytokines such as IL-4 and IL-17." (PMID 34248677, 2021). "The interaction between IL-4 and its corresponding receptor crucially functions in the pathological process of AR and asthma." (PMID 33834211, 2021). "In contrast to some models that measured IL-4, in our model we measured the Th2 response through IL-5 and IL-13, because they were able to envelop the parameters of asthma." (PMID 34829186, 2021). "On the other hand, Descurainia sophia seeds extract decreased the expression of IL-4, a major marker of type 2 helper T response and inflammation, in mouse model of asthma." (PMID 34400939, 2021). "Th2 cytokines, such as interleukin-4 (IL-4), IL-5, and IL-13, can initiate and sustain important pathophysiological features of asthma." (PMID 33806085, 2021). "Eosinophilic inflammatory response, which is characteristic of asthma, is known to be induced by IL-4, IL-5, and IL-13 produced by CD4+ T helper type 2 (Th2) cells." (PMID 34576095, 2021). "Chymase has been assigned a plethora of asthma-related activities, including increasing mucus production, modification of extracellular matrix and modulation of cytokines like IL-33, IL-4, and IL-1β." (PMID 34868033, 2021).
asthma (continued). "As expected, we successfully induced asthma in rats evident by pathological features and changes in the systemic levels of IL-4 and INF-γ." (PMID 33995948, 2021). "IL-4 is known to play a crucial role the pathogenesis of asthma and other inflammatory responses arising from respiratory infection." (PMID 34226412, 2021). "However, in asthmatic individuals, RV infections have been shown to induce increased levels of interleukin (IL)-4 and IL-13, along with an increased infiltration of macrophages and neutrophils on the respiratory tract, which is linked to the ability of RV to enhance asthma exacerbations." (PMID 34571943, 2021). "We also captured some significant overlaps of asthma disease features in the terms of pathways, of which the overlapping regulation of inflammation and airway remodeling in Interleukin-4 and Interleukin-13 signaling was especially elaborated." (PMID 34970542, 2021). "For example, iNKT cell-derived IFNγ showed a protective effect against Th2-related diseases such as asthma, whereas iNKT cell-derived IL4 increased the pathogenicity of asthma." (PMID 34829848, 2021). "Type 2-driven asthma is a subtype of asthma in which there is a notable release of interleukin-4 (IL4), IL5, and IL13 from cells of both innate and adaptive immune systems." (PMID 34575604, 2021). "It has been reported that filaggrin can be depressed by Th2 cytokines such as IL-4 which play an important role in the pathogenesis of asthma and AD." (PMID 34484176, 2021). "Vaccination against mouse IL-4 partially reduced IgE levels and eosinophilia with minor effects on mucus hypersecretion in a mouse asthma model." (PMID 33976140, 2021). "Increased serum levels of IL-8, as well IL-4, IL-5, and IL-9 have been reported in asthma hyperreactivity following Th2 lymphocyte release." (PMID 34884340, 2021). "On the other hand, it is known that recruitment of Th2 cells that secrete IL-4, IL-5 and IL-13 accompanied by eosinophil recruitment to the airways has been considered integral to the pathogenesis of asthma." (PMID 33407843, 2021). "Previous mouse models of both acute and chronic induced asthma inflammation presented elevated levels of IL-4 in BALF." (PMID 34209324, 2021). "Relating to asthma, IL-4 is known to induce the differentiation of naïve CD4 T cells into Th2 cells and drives the immunoglobulin (Ig) class switch to IgG1 and IgE in B cells." (PMID 33917396, 2021). "Biologics targeting eosinophilic inflammation have been successful for treating severe asthma, and several cytokines, including IL-4, IL-5, and IL-13, have demonstrated promising therapeutic effects in patients with COPD." (PMID 34829866, 2021). "Various effector cells (mast cells, neutrophils, eosinophils, lymphocytes, and epithelial cells) and cytokines (IL-4, -5, -6, -9, -13, -25, and -33) are known to play important roles in the inflammatory response of asthma." (PMID 34079051, 2021). "A positive correlation was found between serum miR-21 and IL-4, confirming the role of this miRNA in Th2 activation and asthma pathogenesis." (PMID 33478047, 2021). "The extent to which the protective effects of anti-IL-4 and IL-13 therapy in asthma reflects local blockade of the cytokines in the lung vs. systemic effects is still not fully understood." (PMID 33976140, 2021). "The standard of care for allergic asthma consists of inhaled corticosteroids and short- and long-acting bronchodilators, which control asthma symptoms in the majority of patients, complemented by anti-IL4 and anti-IL5 pathway therapies." (PMID 33918602, 2021). "ILC2 production of IL-4 blocks Treg induction in food allergy responses, however this has yet to be shown in asthma." (PMID 34630416, 2021). "Due to its ability to relay signals for both IL-4 and IL-13, the blockade of IL-4Rα signalling has been of interest for alleviating asthma symptoms and severity." (PMID 33653328, 2021).